MS4A12 (membrane spanning 4-domains A12)
Description:
May be involved in signal transduction as a component of a multimeric receptor complex.
Synonyms: Ms4a10; FLJ20217
Tractability: Antibody: UniProt predicts a signal peptide or a membrane-spanning region; its Gene Ontology location is reachable by antibodies, with medium confidence; the Human Protein Atlas places it where antibodies can reach.
Gene: Protein-coding gene on chromosome 11 (60,492,722 to 60,507,535, forward strand). Ensembl gene ENSG00000071203.
Subcellular location: Membrane
Subcellular location (Human Protein Atlas): Cytosol; Plasma membrane; Endoplasmic reticulum; Golgi apparatus; Nucleoli
Gene Ontology:
Molecular function: protein binding
Biological process: cell surface receptor signaling pathway
Cellular component: plasma membrane; membrane
Genetic constraint (gnomAD): Loss-of-function variants: 29 observed, 24.9 expected, observed/expected ratio (o/e) 1.16, 90% interval 0.87 to 1.59. The upper end of that interval is the gene's LOEUF score, 1.59, which puts it in group 6 of 6, group 1 being the genes least tolerant of losing a copy. Missense variants: 342 observed, 344.47 expected, observed/expected ratio (o/e) 0.99, 90% interval 0.91 to 1.09. Synonymous variants: 108 observed, 115.49 expected, observed/expected ratio (o/e) 0.94, 90% interval 0.8 to 1.1.
Homologues: Orthologues: chimpanzee MS4A12 (97% identical), rabbit MS4A12 (63% identical), pig MS4A12 (58% identical), rat Ms4a12 (52% identical), mouse Ms4a12 (51% identical). Paralogues in human: MS4A8 (34% identical), MS4A18 (30% identical), MS4A15 (29% identical), MS4A4A (22% identical), MS4A6A (22% identical), MS4A1 (20% identical), MS4A14 (18% identical), MS4A3 (18% identical), MS4A10 (18% identical), MS4A2 (18% identical), MS4A7 (18% identical), MS4A5 (17% identical), and 4 more.
Diseases named in the same sentence as MS4A12 in open-access papers:
MS4A12 is named in the same sentence as 9 diseases in open-access papers, as found by Europe PMC text mining. Sharing a sentence is not in itself a finding about the gene and the disease. The quoted sentences say what the papers report.
colon cancer (10 papers, 2009 to 2024). "MS4A12 is a novel component of store-operated [Ca2+] entry in intestinal cells, and loss of MS4A12 in LoVo colon cancer cells attenuates epidermal growth factor receptor-mediated signaling, thereby promoting colonic carcinoma migration." (PMID 39717774, 2024). "Colon cancer-associated MS4A12 is a novel colon-specific component of store-operated Ca2+ (SOC) entry sensitizing cells for epidermal growth factor (EGF)-mediated effects on proliferation and chemotaxis." (PMID 19781065, 2009). "MS4A12 is exclusively expressed in the mucosal epithelial cells of colonic tissue and in colon cancer cell lines." (PMID 39717774, 2024). "MS4A12 also functions in modulating EGFR signalling, the main tumour-promoting factor in colon cancer, causing tumour growth and survival, whereas loss of MS4A12 protein deteriorated EGFR-dependent cell functions." (PMID 34573430, 2021). "In the course of malignant transformation expression of MS4A12 is frequently and strongly maintained in colon cancers." (PMID 19781065, 2009). "Similarly, 2 other variants identified in patient 6, membrane-spanning 4-domains, subfamily a, member 12 (MS4A12) and protein phosphatase 1 regulatory subunit 32 (PPP1R32), are associated with colon cancer and ciliary movements, respectively." (PMID 37943610, 2024). "The colon-specific expression of MS4A12 makes it a potential target for colon cancer immunotherapy." (PMID 32462020, 2020). "He found that MS4A12 participated in the differentiation of colon cancer cells." (PMID 32797167, 2020). "RNA interference (RNAi)-mediated silencing of intestine-specific transcription factors CDX1 and CDX2 and chromatin immunoprecipitation (ChIP) in LoVo and SW48 colon cancer cells revealed that MS4A12 transcript and protein expression is essentially dependent on the presence of endogenous CDX2." (PMID 19781065, 2009). "MS4A12 gene belonging to the MS4A family encodes a protein found in the apical membrane of colonocytes that plays an important role in the differentiation, proliferation, and cell cycle regulation and is believed to be a risk classification marker for early-stage colon cancer." (PMID 36991484, 2023). "We thus compared with the same gene expressions (up-regulated transcripts: SLC16A4, DSC3, ALDOB, EPHX4, ARHGAP24; and down-regulated transcripts (MS4A12, TMIGD1, CASP5) in 5 colon cancer lines: HCT 116, Caco2, HT-29, Lovo, and C32." (PMID 25929336, 2015). "To directly assess the impact of CDX1 and CDX2 on MS4A12 transcript and protein expression we silenced both factors in LoVo and SW48 colon cancer cells by transient transfection with specific siRNA duplexes." (PMID 19781065, 2009).
colorectal cancer (4 papers, 2015 to 2024). A primary or metastatic malignant neoplasm that affects the colon or rectum. "Multiple genes can be used as molecular markers to distinguish between colon adenomatous polyps and cancer, and that MS4A12 can be used as an early diagnostic target for colorectal cancer." (PMID 32797167, 2020). "The rate of MS4A12 positivity in colorectal cancer is as high as 63%, and MS4A12 expression is regulated by the transcription factor caudal type homeobox 2 (CDX2), which can influence the proliferation and cell cycle of colorectal cancer cells." (PMID 39717774, 2024). "Analysis using qRT-PCR has shown that SST, CXCL8, and MS4A12 were significant differentially expressed between colorectal cancer tissues and normal colorectal tissues (P < 0.05)." (PMID 32462020, 2020). "MS4A12 is elevated in colorectal cancer, but down-regulated in our PMP samples despite being a known CDX2 transcriptional target, often up-regulated in PMP." (PMID 25929336, 2015). "MS4A12 may promote the proliferation and invasion of colorectal cancer cells by influencing epidermal growth factor receptor." (PMID 32797167, 2020). "In addition, 3 core genes (SST, CXCL8, and MS4A12) were found to be significantly differentially expressed between colorectal cancer tissue and normal colorectal tissue using qRT-PCR." (PMID 32462020, 2020). "Further studies found that intestinal specific transcription factor CDX2 mediated by RNA interference (RNAi) is a trans-activator of growth-promoting gene expression in colorectal cancer, suggesting that MS4A12 may be a potential therapeutic target for colorectal cancer." (PMID 32797167, 2020). "Quantitative RT-PCR results have shown that the following 3 core genes were significantly different between colorectal cancer tissues and normal colorectal tissues: SST, CXCL8, and MS4A12." (PMID 32462020, 2020). "MS4A12 is specifically expressed in colonic tissue, and early immunohistochemical studies revealed that MS4A12 is expressed exclusively in colorectal cancer cells, with no expression in adjacent stromal or nontumor epithelial cells." (PMID 39717774, 2024). "However, no research has explored the relationship between MS4A12 and the occurrence of colorectal cancer." (PMID 32462020, 2020).
cancer (4 papers, 2014 to 2023). A tumor composed of atypical neoplastic, often pleomorphic cells that invade other tissues. "There was heterogeneity in cancer cells, and found that MS4A12 and other genes could be used to predict cancer patients, suggesting that MS4A12 might be a potential diagnostic target." (PMID 32797167, 2020). "The TF-protein NFKB1 (a regulator of GUCA2A, CA4, CEMIP and MS4A12) is a suppressor of inflammation, ageing and cancer." (PMID 36991484, 2023). "Therefore, CLCA4 and MS4A12 might be cancer suppressors which could be beneficial to the progression of patients with PCRC." (PMID 32797167, 2020). "Indeed aberrant gene transcription of some markers associated with carcinogenesis, NOX1, LGR5, MS4A12, reveal greatest deviation from that of normal tissue in the adenomatous polyps prior to development of carcinoma." (PMID 25423035, 2014). "ACTG2, EZR, CNN1, DES, MS4A12 and NTN1 are all expressed at significantly higher levels in normal tissue compared to adenomatous polyp or carcinoma tissues." (PMID 25423035, 2014). "Meanwhile, survival analysis of PCRC patients showed that patients with low expression of MS4A12 had worse survival than those with high expression of MS4A12, suggesting that MS4A12 was involved in the occurrence and development of PCRC and could inhibit the progression of cancer." (PMID 32797167, 2020). "Similarly, expression of MS4A12 is absent in most areas of carcinoma tissue, but when visible, in areas with more regular and differentiated epithelial structure, expression appears more intense than that seen over adenomatous polyp tissues." (PMID 25423035, 2014).
MS4A12 also shares sentences with these, for which no sentence is quoted: tumor (3 papers); adenoma (1); chronic obstructive pulmonary disease (1); colon adenomatous polyps (1); colonic carcinoma (1); colorectal adenoma (1).